INS (insulin)
Diseases named in the same sentence as INS in open-access papers (continued):
Sharing a sentence is not in itself a finding about the gene and the disease.
diabetes (continued). "The current management of Type 2 Diabetes Mellitus (T2DM) includes incretin-based treatments able to enhance insulin secretion and peripheral insulin sensitivity as well as improve body mass, inflammation, plasma lipids, blood pressure, and cardiovascular outcomes." (PMID 35056417, 2022). "This is at odds with the proposed action on stimulating CD8+ T-cell function, however in an already diabetic context, the use of insulin may be a sign of progressed diabetes and thus an overall less healthy metabolic status of the patient." (PMID 35957811, 2022). "However, different from Cyp2r1, the diabetes-induced regulation of Pgc-1α and that of a GR target gene Tat was normalized by insulin treatment." (PMID 35524739, 2022). "AIR Insulin exhibited comparable efficacy as the standard subcutaneously injected insulin in clinical studies, which may appeal to diabetes patients." (PMID 36071354, 2022). "We finally investigated the possibility that changes in beta cell insulin sensitivity could reduce the insulin secretion during diabetes development." (PMID 36589856, 2022). "Recently, a list of bioactive peptides with antidiabetic potential has been identified in dietary proteins, which could improve insulin uptake, decrease blood glucose levels, and inhibit key enzymes involved in the development and progression of diabetes." (PMID 35334901, 2022). "Therefore, in this patient population with diabetes, insulin pumps and continuous delivery devices certainly can facilitate improving adherence, and consequently, glycemic control." (PMID 35831938, 2022). "The lack of tissue sensitivity to insulin, that is, insulin resistance, as well as defective secretion of this hormone is associated with type 2 diabetes mellitus (T2DM), defined now as a pandemic of the 21st century." (PMID 35565918, 2022). "Lower mobilization of HSC and higher mobilization of VSEL detected at the clinical onset of diabetes might become indicators of more efficient insulin production at that specific time point." (PMID 34510360, 2022). "However, global over-expression of AGER1 increased urinary AGE clearance and improved insulin effectiveness in experimental diabetes in mice, but resulted in increased tubulointerstitial fibrosis." (PMID 35807857, 2022). "To conclude, drugs that increase insulin sensitivity might have a positive effect on the cognitive consequences of diabetes." (PMID 35958117, 2022). "Altered insulin-mediated signaling and brain glucose hypometabolism are characteristic signs observed in the brains of patients with certain neurological diseases, but also others such as type 2 diabetes mellitus and vascular diseases." (PMID 35615716, 2022). "There is evidence suggesting that oleanolic acid might be effective against dyslipidemia, diabetes and metabolic syndrome, through enhancing insulin response, preserving the functionality and survival of β-cells and protecting against diabetes complications." (PMID 35276982, 2022). "Although the study was small, this suggests NPH insulin may be used to control diabetes mellitus in dogs successfully." (PMID 35152907, 2022). "To conclude, in the present study we have shown that using the new technologies for insulin delivery may be beneficial in achieving target glucose control and alleviating the diabetes burden during pregnancy." (PMID 36422278, 2022). "ACE2 deficiency has been directly linked to defects in Insulin secretion and interestingly, B1R as well as CPN1, the enzyme that converts BK into the B1R ligand DABK have been researched as preclinical targets in the context of Diabetes." (PMID 39086962, 2022). "GCLC increased in the insulin resistant hearts but decreased following the onset of diabetes." (PMID 35624791, 2022). "Therefore, for patients with hyperglycemic urgency or very poorly controlled diabetes mellitus, insulin is the first-line therapy, although it increases the risk of hypoglycemia." (PMID 36463197, 2022).
diabetes (continued). "The hypoglycaemic action of Zea mays extracts correlated with the modulation of diabetes-related enzymes with “α-glucosidase inhibition” led to further improvements in insulin sensitivity in adipocytes, suggesting a synergistic action." (PMID 36080269, 2022). "In contrast, the metabolic response to iron overload is tightly regulated by DMT1, and inhibition of DMT1 or iron restriction improved the glucose tolerance and circulating insulin levels in high-fat diet-induced diabetes and multiple low-dose streptozotocin-induced islet inflammation." (PMID 36430158, 2022). "Given pandemic-related interruptions in care, delayed access to glucose-lowering medications, including insulin, may have contributed to worsening glycemic management and an overall increase in diabetes-related complications." (PMID 36286591, 2022). "Phloridzin is a naturally occurring non-selective SGLT2 inhibitor, which was first associated with diabetes in the 1980s, when found to correct hyperglycemia and normalize insulin sensitivity without altering insulin levels in diabetic rats." (PMID 36686683, 2022). "However, the relative influence of insulin treatment seemed to be of smaller impact in women with subsequent diabetes." (PMID 36085031, 2022). "This is exacerbated in patients on insulin and particularly in patients with uncontrolled diabetes." (PMID 35165639, 2022). "FXR stimulates the secretion of fibroblast growth factor 19 into the portal circulation and activates its fibroblast growth factor 4 liver receptor, leading to decreased gluconeogenesis glycemia and improved insulin sensitivity and glucose and lipid metabolism in diabetes." (PMID 35907885, 2022). "Fifty-nine percent of NH residents with diabetes are treated with insulin." (PMID 35600866, 2022). "Type 2 diabetes mellitus (T2DM) is a chronic metabolic disorder associated with beta-cell dysfunction which emanates impaired insulin secretion, resistance to peripheral actions of insulin, or both, producing interminable hyperglycemia." (PMID 36014373, 2022). "Increasing this flipping efficiency can alleviate the impaired insulin secretion in diabetes." (PMID 36316316, 2022). "In the diabetes group, islets were in irregular shape and insulin positive cells were dispersedly expressed in the islet (dotted line), some cells outside of the islet were also positively stained with insulin (black arrow)." (PMID 35858880, 2022). "However, the mean heart rate decreased with diabetes, and declined even further with insulin treatment." (PMID 35574440, 2022). "This led to the establishment of the insulinocentric view, which proposes that all diabetes-related metabolic disorders are directly caused by a lack of insulin secretion." (PMID 35784565, 2022). "Novel insulin dosing strategies may lead to improved outcomes for persons with diabetes during Ramadan." (PMID 35634376, 2022). "Controlling insulin secretory function by regulating the Sdc4 gene expression may also be a target for diabetes therapy." (PMID 36292936, 2022). "Type 1 diabetes, which is a form of diabetes mellitus, is caused by a lack of insulin due to the problem in β-cells producing insulin in the islets of Langerhans of the pancreas." (PMID 35911103, 2022). "Experiments in rat models of diabetes are suggestive of impaired counter-regulatory glucagon secretion during insulin-induced hypoglycaemia due to increased somatostatin signalling, the effects of which can be reversed by somatostatin receptor 2 antagonism (SSTR2a)." (PMID 36147573, 2022). "The researchers reported that glycated insulin (corresponding probably to the Schiff base) was less biologically active and so might contribute to glucose intolerance in people with diabetes." (PMID 35631667, 2022). "Clinically, insulin administration remains the major method of diabetes mellitus management." (PMID 35730406, 2022).
diabetes (continued). "Finally, despite the increased insulin sensitivity, we observed increased hepatic glucose production in senescent cells which is a key feature of diabetes and contributes to elevated glucose levels." (PMID 36072934, 2022). "According to the findings, people who have had diabetes for over 10 years, used insulin either solely or in combination with an oral hypoglycaemic agent (OHA) or have a history of chronic kidney diseases showed an increased prevalence of hypertension (p < 0.001)." (PMID 35093064, 2022). "Insulin transmission, production and secretion, and insulin responsiveness in the peripheral muscle are all known to be altered with mitochondrial dysfunction in diabetes." (PMID 36187456, 2022). "Given that CPAP therapy use for OSA treatment may be beneficial for controlling systemic glycemic and insulin levels, it is plausible that it could also improve ocular outcomes in patients with diabetes." (PMID 35263016, 2022). "It is worth noting that although IR does not necessarily cause T2D, metformin, a drug commonly used in diabetes treatment, does not improve insulin sensitivity and renders the treatment for IR ineffective." (PMID 35744089, 2022). "A growing number of studies suggest that abnormal thyroid function may impact glucose metabolism, insulin sensitivity, and the development of chronic complications of diabetes." (PMID 36465631, 2022). "This treatment protects the liver against hepatic damage through the inhibition of endoplasmic reticulum stress in fructose-fed rats and has anti-diabetes effects through ameliorating insulin resistance via the hepatic HIF-insulin signaling pathway in type-2 diabetic rats." (PMID 36294970, 2022). "Scatter plot of the blood glucose level of all subjects (at the time of admission, minimum, maximum values during hospitalization, and at discharge, respectively) and the distribution of blood glucose levels according to the presence of diabetes or insulin use were presented." (PMID 36575485, 2022). "The different action of PAS on the two main regulators of glucose metabolism strengthens the idea that an impaired insulin:glucagon ratio may be the pathophysiological basis of PAS-related diabetes." (PMID 35563608, 2022). "In some cases, strategies to reduce costs may improve adherence, and initiation of insulin therapy earlier may improve the health and well-being of patients with diabetes." (PMID 36556420, 2022). "In this study, the high-risk group for adolescent diabetes was 22.7% among South Korean adolescents, and the high-risk groups for diabetes showed increased physiological and biochemical indicators (SBP, FPG, HbA1c, insulin, TG, uric acid)." (PMID 36010139, 2022). "Glucagon-like peptide-1 receptor agonists (GLP-1RAs) are a class of injective anti-diabetes agents that lower blood glucose levels, enhancing insulin secretion in response to nutrient ingestion, without risk of hypoglycemia." (PMID 35204778, 2022). "This review provides insights on the development of insulin treatment for diabetes mellitus that may be useful for clinicians in meeting the needs of their individual patients." (PMID 35890301, 2022). "In animals where diabetes is induced after implants have been allowed to osseointegrate, insulin administration tends to have a protective effect on RTQ but without a detectable variation in BIC between normoglycaemic and hyperglycaemic (treated or untreated) animals." (PMID 36276721, 2022). "Treatment diabetes before DKA episode mostly used insulin 58.6% (T1DM 82.6, T2DM 37.7%)." (PMID 34986830, 2022). "Patients with diabetes may be vulnerable to sarcopenia due to primary changes in insulin level and activity." (PMID 36482911, 2022). "Pancreatic β-cells are the producer of insulin, thus destruction of these cells e.g., via apoptosis and/or oxidative stress, may contribute to diabetes." (PMID 36499769, 2022).
diabetes (continued). "This may be the case for the specific ethnic group of patients with type 2 diabetes mellitus under insulin treatment, leading to a different result." (PMID 36292529, 2022). "CAC = 0 identified patients with a low risk of having a cardiac event, regardless of diabetes duration, insulin use, or glycemic control." (PMID 36233709, 2022). "The combination of L. acidophilus and B. lactis can also significantly reduce fasting blood glucose and serum insulin concentrations in patients with diabetic nephropathy and diabetes with IHD, increase insulin sensitivity, reduce triglyceride levels and TC/HDL-C ratio, and increase HDL-C levels." (PMID 35656118, 2022). "Furthermore, we showed that targeting the flipping efficiency of Stx2 profoundly modulated insulin secretion, which would benefit restoring the impaired insulin secretion in diabetes." (PMID 36316316, 2022). "Notably, following extensive research in the last decades on insulin delivery systems, the International Society for Pediatric and Adolescents Diabetes (ISPAD) advocated for insulin pump therapy for diabetes management in children of all ages." (PMID 36422210, 2022). "Moreover, we will discuss the most frequently used animal models in diabetes and AD studies, which enabled the understanding of the mechanism of action of compromised insulin activity-related pathologies." (PMID 36232867, 2022). "The results showed that fasting PP was positively correlated with the course of diabetes and AUCbg (r = 0.256, r = 0.243, r = 0.257, p < 0.05), and was negatively correlated with 60 min postprandial C‐P, 60 min postprandial insulin, and fasting GLP‐1 (r = −0.248, r = −0.235, r = −0.207, p < 0.05)." (PMID 35437937, 2022). "GLP-1 is released after food intake and acts to amplify glucose-dependent insulin secretion, and it has been in the spotlight as a target for the treatment of obesity and diabetes as its positive effects on glucose homeostasis, appetite regulation, gastric emptying and postprandial lipid metabolism." (PMID 35583337, 2022). "Prolonged hyperglycemia followed by an increase in insulin secretion may disturb pancreatic β-cell function and results in glucose intolerance and the development of diabetes consequently." (PMID 36253802, 2022). "However, in comparison with insulin, which mainly acts on blood sugar stabilization and diabetes treatment, more effective biological drugs are warranted to improve UPEC infection in the urinary tract in a high-glucose environment." (PMID 36555403, 2022). "Such experimental evidence may implicate ADM as a fundamental factor in maintaining insulin homeostasis and normoglycemia, and dysregulation of ADM maybe one of the causal factors in diabetes." (PMID 35324977, 2022). "After six months, 2, and 5 years insulin sensitivity is augmented and diabetes remission occurs." (PMID 36432612, 2022). "With the backdrop of diabetes in rats, it is further noted that there is reduction in oxidative stress markers in the blood in addition to the improvement of blood glucose, cholesterol and insulin profile." (PMID 36302045, 2022). "Some of these joint effects supported the findings of a USA study, which revealed that the effects are pronounced for individuals diagnosed with early-onset diabetes, reported living with diabetes for a longer duration, and used oral glucose-lowering medication and insulin." (PMID 35477572, 2022). "Moreover, adolescents are often reluctant to accept recommendations for increasing SMBG or insulin doses when they feel that it increases their diabetes-related distress and burden." (PMID 36992766, 2022). "This commentary aims to provide comprehensive insight with historical context into intersectional components of diabetes in the global arena through analyses of insulin affordability, coupled with the critical role of nutrition intervention after searching the PubMed for relevant articles." (PMID 35546683, 2022). "Most dispensed pharmaceuticals are insulin and anti‐diabetes drugs." (PMID 36177396, 2022).
diabetes (continued). "The gold standard for the treatment of diabetes would be wearable biosensors with improved specificity and sensitivity, and of a low detection limit for the precision delivery, aside from overcoming the challenge of the oral delivery of insulin." (PMID 36139035, 2022). "Future research should look into the effect of aerobic exercises in PCOS patients with diabetes mellitus to see whether improving insulin resistance has similar effects on blood glucose levels." (PMID 35547420, 2022). "Insulin resistance beta-cells of the pancreas lead to overt diabetes in rats; hence, the treatment that sensitizes beta-cells to insulin may shield diabetic patients from beta-cell failure." (PMID 36381916, 2022). "Furthermore, several findings stand against the idea that hyperglycemia of diabetes has driven the observed relationship of insulin secretory indices with adult height." (PMID 35358060, 2022). "However, mean age for newly diagnosed diabetes was 43y in the β-Cell-Failure group and 45y in the Insulin-Resistance group, thus MODY is unlikely." (PMID 36211668, 2022). "Although the pathogenesis of diabetes used to be considered to involve inadequate insulin production due to the destruction of β cells, recent findings have suggested that the disruption of pancreatic islet microcirculation can contribute to the pathogenesis and development of diabetes." (PMID 35139776, 2022). "It is also essential to take the right insulin or other diabetes medication doses (p < 0.001)." (PMID 35160077, 2022). "In addition, both boys and girls were included, and DEBs were assessed with a diabetes‐specific measure, which ensured a direct evaluation of purging behaviors unique to T1D, such as insulin omission/reduction." (PMID 35751499, 2022). "Its extract increases insulin-induced glucose uptake, suggesting that this herb could contribute to the treatment of diabetes." (PMID 35226829, 2022). "Diabetes is a sort of metabolic disorder accrued due to hyperglycemia with raising of glucose levels in the blood, caused by a lack of insulin or a reduction in the insulin level." (PMID 36235263, 2022). "Indeed, decreased trophic factors such as insulin growth factor in the liver due to liver toxicity or chronic diseases including diabetes my result in osteoblast dysfunction." (PMID 35487926, 2022). "PKM1/2, PI3K, p-AKT, and GLUT4 play a vital role in the insulin signaling pathway in diabetes." (PMID 35282429, 2022). "This may be related to the established phenomenon of sex differences in glucose homeostasis; males have decreased insulin sensitivity compared to females as well as increased incidence of diabetes." (PMID 35740596, 2022). "However, the rate of AGEs clearance is often greatly altered in individuals with diabetes who also have impairments in either kidney or liver function influencing insulin secretion and sensitivity." (PMID 36359899, 2022). "Whether and how changes in the amylin to insulin ratio may affect the pathogenesis or the progression of diabetes, remains unknown, however." (PMID 35456307, 2022). "Since decreasing the C16:0/C18:1 value improves insulin sensitivity in humans, this could be an effective method to reduce the blood sugar concentration and control diabetes." (PMID 36687606, 2022). "One key question in these studies is whether the positive effects of insulin-sensitizing medications occur only in people with IR or diabetes or whether these medications could help even individuals with mood disorders who do not suffer from MetS." (PMID 36347837, 2022). "Overall, this cross-sectional analysis shows a positive association of dietary manganese with insulin sensitivity that remained significant in all adjusted models in adults without diabetes and remained significant in minimally adjusted model in T1D group." (PMID 35789593, 2022).